TLR7 (toll like receptor 7)
Diseases named in the same sentence as TLR7 in open-access papers (continued):
Sharing a sentence is not in itself a finding about the gene and the disease.
COVID-19 (continued). "The GEO dataset results showed that the TLR7 detected in samples of mice infected with COVID-19 increased, which was consistent with the response of cytoplasmic nucleic acid receptors to recognize intracellular damage caused by exogenous pathogen infection." (PMID 37362864, 2023). "A potential new target for COVID-19 treatment was TLR7, a critical component of COVID-19 infection and progression." (PMID 37362864, 2023). "•Significance of the study: In this study, revealing the roles of TLR7, a nucleic acid sensor for COVID-19 in pan-cancer." (PMID 37362864, 2023). "As an immune-related biomarker, TLR7 can diagnose and predict the prognosis of cancer patients with COVID-19 and is a potential therapeutic target for these patients." (PMID 37362864, 2023). "Our results showed that COVID-19 patient–derived EVs induced NETs formation by activating TLR7/8 to promote NADPH oxidase-dependent ROS production." (PMID 37904132, 2023). "Another study showed that the TLR7 rs3853839 GG genotype was considerably more prevalent in COVID-19 patients (38.7%) than in the control individuals (4.4%)." (PMID 38066751, 2023). "The COVID-19 patient–derived EV-induced NETs formation was reduced in TLR7- and TLR8- knockdown cells, respectively." (PMID 37904132, 2023). "•New findings: In this study, we proposed a computational framework to comprehensively study the roles of TLR7 in COVID-19 and pan-cancers at genetic, gene expression, protein, epigenetic, and single-cell levels." (PMID 37362864, 2023). "In X-linked Toll-like receptor 7 (TLR7) deficiency, and thus exclusively affecting males, an increased risk of severe or fatal COVID-19 has also been found." (PMID 37515137, 2023). "In this study, we proposed a computational framework to comprehensively study the roles of TLR7 in COVID-19 and pan-cancers at genetic, gene expression, protein, epigenetic, and single-cell levels." (PMID 37362864, 2023). "Several studies have identified numerous genetic variants correlated with COVID-19 severity, including ACE2, ABO, CD26, IFITM3, HLA, TLR7, and TMPRSS2." (PMID 38138892, 2023). "It has also been demonstrated in nasal tissue, bronchoalveolar lavage and peripheral blood mononuclear cells extracted from COVID-19 patients that expression levels of TLR7 correlated with disease severity." (PMID 35986347, 2022). "This identifies the pDC-macrophage circuit as critical for the pathogenesis of COVID-19 and identifies the TLR7 sensing of SARS-CoV-2 by pDCs as a central element of the immune response to this virus." (PMID 36083891, 2022). "Meanwhile, in severe COVID-19 patients, TLR7 decreases its expression because SARS-CoV-2 has the ability to inhibit pathways associated with the secretion of IFN-α/β." (PMID 36325317, 2022). "The self-adjuvanting peptide vaccine conjugated with TLR7 agonists is a novel form of vaccine that has the potential to be applied for COVID-19 or other infectious diseases and can serve as a rapid response strategic reserve for future outbreaks." (PMID 35102138, 2022). "Although it is likely that the intrinsic difference in TLR7 dosage between men and women is part of the explanation for the male sex bias in severe COVID-19, the possible additional effect of common genetic variation in TLR7 should be further investigated." (PMID 35986347, 2022). "It has been suggested that TLR7 is able to stimulate the NET formation in COVID‐19 subjects and triggering of the TLR7/8 complex is capable of inducing powerful pro‐inflammatory response in COVID-19 patients, culminating in acute lung injury." (PMID 35538443, 2022). "Ethnicity disparity in COVID-19 mortality rates were suggested to be explained in part by elevated gene expression of TLR7 and TLR9." (PMID 35956081, 2022).
COVID-19 (continued). "The findings of STING, IRF3, and TLR7 upregulation in different cell-types in villous tissue of COVID-19 exposed placentas suggest that cells at the placental maternal-fetal interface react differently in response to maternal COVID-19 infection." (PMID 36743911, 2022). "The Described study is in accordance with previous findings focusing on the role of TLR7 and CXCL10, which is directly associated with TLR7 in severe course of COVID-19." (PMID 35409036, 2022). "In an analysis comprising 5,085 participants with severe COVID-19 and 571,737 controls, we found that the gene for toll-like receptor 7 (TLR7) on chromosome X was an important determinant of severe COVID-19." (PMID 36327219, 2022). "Genetic mutations TLR3, TLR7, and IRF7-dependent and neutralizing autoantibodies inhibited type I interferon signaling in COVID-19 patients who had severe disease." (PMID 36726976, 2022). "TLR7 is considered a key cellular sensor of SARS-CoV-2 encoded ssRNA, and it is involved in host resistance and disease pathogenesis of COVID-19." (PMID 36329841, 2022). "It is thought that the production of proinflammatory cytokines is induced by the activation of different TLRs, such as TLR2, TLR4, and TLR7/8, which greatly contributes to the pathogenesis of COVID-19 and its severity." (PMID 35832809, 2022). "Among the extracted ultra-rare variants there was a group of genes, such as TLR3, TLR7 and TICAM1, already shown to be directly involved in the Mendelian-like forms of COVID-19." (PMID 34889978, 2022). "Upregulation of TLR7 expression was also seen in stromal cells and fetal endothelial cells in COVID-19 exposed placentas (h and h1)." (PMID 36743911, 2022). "The expression of TLR4 and TLR7 was found to be significantly upregulated in mucosal membrane cells in the children with COVID-19; same study reported expression of pro-inflammatory cytokines at both the transcriptional and translational levels." (PMID 35847031, 2022). "At the same time, robust and uncontrolled TLR7 signaling can contribute to a cytokine storm and sever COVID-19 as well as to autoimmunity." (PMID 36389822, 2022). "Consistent with this, rare pathogenic variants in TLR7 and eight candidate loci, including, TLR3, IRF3, and IRF7 governing type I IFN response have been identified in patients with critical COVID-19." (PMID 36143338, 2022). "Taken together, these experiments demonstrate that the ability of monocytes to mount an appropriate proinflammatory response is impaired in patients with severe COVID-19 upon stimulation through TLR4 or TLR7/8." (PMID 35380990, 2022). "As sex-determined variables are currently understudied, and the effects of other X-related immune genes and TLR7 modulators are unclear, future research should consider to shed more light on the sex bias in COVID-19." (PMID 34858409, 2021). "Both variants were associated with impaired type I and II IFN responses upon stimulation with the TLR7 agonist imiquimod, supporting the importance of intact TLR7 signaling in COVID-19 pathogenesis." (PMID 34367187, 2021). "In COVID-19, TLR7 in plasmacytoid dendritic cells is one of the pattern recognition receptors responsible for IFN production and a delayed IFN response has been associated with immunopathogenesis and mortality." (PMID 34858409, 2021). "Recent studies on mesenchymal stem cells (MSC) revealed that MSCs can contribute to the pathogenesis of SARS-CoV-2 by elevating anti-inflammatory cytokines and M2 macrophages (anti-inflammatory phenotype), especially TLR-7 pathways in COVID-19 patients." (PMID 34659656, 2021). "Recent research in adult SARS-CoV-2 cases has identified associations between severe COVID-19 and several rare genetic variants in genes implicated in TLR3-, TLR7-, and IRF7-dependent IFN type I immunity, including heterozygous variants in the gene TBK14–7." (PMID 34210994, 2021). "Studies exploring COVID-19 treatment via the TLR7-mediated IFN pathway should consider this sex difference." (PMID 34858409, 2021).
COVID-19 (continued). "Imiquimod is a dual TLR7/8 agonist, which has been suggested as a potential pharmaceutical treatment for COVID-19 patients." (PMID 33498183, 2021). "In this study, several pharmacological effects of the TLR7 agonist imiquimod on HBECs from asthmatics, of interest for the treatment of both viral induced asthma exacerbations and COVID-19, have been demonstrated." (PMID 34950134, 2021). "Mechanistically, monocyte-elevated expression of Toll-like receptor 7 (TLR7) and Bruton tyrosine kinase (BTK) is associated with severe outcomes in males with COVID-19." (PMID 34330889, 2021). "Several BTK inhibitors (e.g., acalabrutinib and ibruitinib, which blocks TLR7-dependent NF-κB activation in monocytes) have been shown to be potentially promising in treatment of patients with severe COVID-19." (PMID 34330889, 2021). "Based on data analysis collected from mice models treated with imiquimod following influenza A infection, imiquimod, a dual TLR7/8 agonist, has been proposed as a viable treatment for COVID-19 patients." (PMID 34770863, 2021). "It is important to investigate the possible roles of PCAF and GCN5 activities in regulating TGF-β and TLR7 signalling pathways in severe COVID-19 for novel treatments to ameliorate the severity and prevent COVID-19 fatalities." (PMID 34691068, 2021). "Several studies have shown that the TLR7 response is critical for favorable outcome of COVID-19, highlighting the clinical importance of the innate immune system in SARS-CoV-2 infection." (PMID 34835108, 2021). "Although TLR-7 and 8 are highly important in COVID-19, other receptors also need to be investigated." (PMID 34659656, 2021). "The clinical observations of deleterious TLR7 mutations and a poor type 1 IFN response identify TLR7 as an important PRR in the immune response against COVID-19." (PMID 34858409, 2021). "There are several more host genetic factors that have been suggested as COVID-19 severity predictors, such as genetic variability in human leucocyte antigen genes, major histocompatibility complex class I genes and TLR7 gene on chromosome X, for example." (PMID 34870573, 2021). "COVID-19 patients showed increased blood levels of pro-inflammatory cytokines and chemokines, which are produced by the TLR7/8 pathways." (PMID 34770863, 2021). "Patients with COVID-19 have shown increased circulating levels of pro-inflammatory cytokines and chemokines, which are produced through the TLR7/8 pathways." (PMID 33498183, 2021). "We propose IFN-I (and TLR7/TLR8) and PAI-1 as potential biomarkers to predict the susceptibility to severe COVID-19." (PMID 34064104, 2021). "In particular, monocyte-elevated expression of two key inflammation-associated genes, TLR7 and BTK, is associated with severe outcomes in males with COVID-19." (PMID 34330889, 2021). "The only set shared by severe COVID-19, influenza-associated ALI/ARDS and sepsis is that comprised of TLR4, TLR7 and NLRP3." (PMID 33672738, 2021). "Furthermore, male identified patients (which typically have low levels of estrogen and only one X chromosome encoding TLR7), are significantly more likely to be hospitalized and develop severe COVID-19, and this could be partly a result of reduced IFN-I production by their pDCs." (PMID 34578420, 2021). "For example, in severe COVID-19, TLR7 (viral) and TLR4 (bacterial/fungal) synergize, TLR9 and TLR4 (both bacterial/fungal) synergize and TLR2 and TLR4 (both bacterial/fungal) synergize with NLRP3 (viral and bacterial)." (PMID 33672738, 2021). "The protective and anti-viral role that TLR7 plays in SARS-CoV-2 infection is further supported by severe COVID-19 outcomes experienced in young men with X-chromosomal TLR7 genetic anomalies." (PMID 33498183, 2021). "Imiquimod, for instance is an activator of TLR7 and has been proposed to enhance the innate and adaptive immunity in early stage COVID-19 patients." (PMID 33519463, 2020).
COVID-19 (continued). "As a result, M5049, a TLR7/8 inhibitor, is currently being tested in clinical trials for the treatment of severe symptoms of COVID-19 as a potential treatment for CRS." (PMID 33149733, 2020). "Imiquimod, a TLR7 agonist, has also been proposed as a therapeutic adjunct for COVID-19 and related infections." (PMID 33679711, 2020). "To this end, we stimulated innate cells and T lymphocytes of COVID-19 patients at admission and before specific treatment with Toll-like receptor 7/8 (TLR 7/8) agonist and anti-CD3, respectively, and we measured the cytokines secreted." (PMID 33585507, 2020). "As TLR7 plays a central role in SARS-CoV-2 detection and the initiation of the innate immune response, several studies have investigated the association between common TLR7 variants and COVID-19." (PMID 40423910, 2025). "This study aimed to identify whether TNF and IFN-γ levels play a central role in regulating the activated state of immune cells in COVID-19 patients and explore potential links with TLR7 and TLR8 signaling." (PMID 39940907, 2025). "TLR7 levels showed a decreasing trend with increased COVID-19 severity, being lower in patients with moderate disease (β-coeff: -0.45 [95%CI -0.65, -0.25], p<0.001) and further reduced in patients with severe disease (β-coeff: -0.69 [95%CI -0.99, -0.40], p<0.001) compared to those with mild disease." (PMID 41445728, 2025). "Moreover, given the similar disease outcomes in TLR7- and IFNAR-deficient humans and mice, we showed that MA-CoV-2-infected mice serve as a reliable model for studying COVID-19 pathogenesis and the antiviral response." (PMID 40162785, 2025). "Furthermore, in mouse models, the early phase of SARS-CoV-2 infection causes an upregulation of the Tlr7, Irf7 and IFN-I pathways in the lungs, whereas Tlr7 and Irf7-deficient mice show increased COVID-19 severity caused by deficient IFN-I and -III activation." (PMID 41445728, 2025). "Peripheral blood mononuclear cells from severe COVID-19 patients who are deficient in TLR7 genes do not respond to the in vitro application of IMQ, contrary to cell cultures from individuals with normal TLR7 genes." (PMID 39062904, 2024). "This suggests that, despite its importance in COVID-19, TLR7 signaling may play a relatively minor role in protecting against CAPA." (PMID 38651925, 2024). "Subsequent candidate gene-, machine learning-, and WES-based rare variant association approaches have generated independent support for the role of TLR7 in severe COVID-19 in males, with recent estimates suggesting the presence of a TLR7 deficiency in around 1–2% of male cases." (PMID 39715278, 2024). "On the other hand, activation of TLRs such as TLR2, TLR4, and TLR7/8 leads to the release of proinflammatory cytokines by cells, a phenomenon which studies have shown to largely determine the development of complications in COVID-19." (PMID 39457048, 2024). "An enrichment in rare nonsynonymous TLR7 variants in patients with critical COVID-19 was reported in another two studies, but the variants were not disclosed and the diagnosis of TLR7 deficiency remains to be confirmed, especially in the women." (PMID 37196358, 2023). "Herein, we demonstrated that COVID-19 patient–derived EVs or viral spike protein triggered-pEVs that carried miR-21/let-7b induced IL-1β/TNF-α/IL-8 upregulation in neutrophils by interacting with TLR7/8 to activate NF-κB." (PMID 37904132, 2023). "Further experiments showed that most TLR7 variants in patients with critical COVID-19, but none of those in mildly infected individuals, were LOF." (PMID 36719370, 2023). "The clinical observations of deleterious TLR7 variants and a poor type I IFN response found in 1–2% across male cohorts of severe cases identify TLR7 as an important PRR in the immune response against COVID-19, especially in younger patients." (PMID 37175768, 2023).
COVID-19 (continued). "We showed that COVID-19 patient–derived EVs or viral spike protein triggered-pEVs that carried GU-enriched miRNAs (e.g., miR-21/let-7b) interacted with TLR7/8 to induce p47phox phosphorylation, activate NADPH oxidase and thus promote ROS production in neutrophils to enhance NETs formation." (PMID 37904132, 2023). "Nevertheless, it is necessary to conclusively affirm the absence of an association between TLR7 (rs864058) polymorphism and susceptibility to COVID-19 in a larger population using more robust statistical power." (PMID 38066751, 2023). "Impaired expression of TLR7/8 has been previously observed in BALs of severe COVID-19 patients." (PMID 36985262, 2023). "In addition, the expression of TLR1, TLR4, TLR5, and TLR8 was significantly elevated in patients with severe or critical COVID-19, and the expression of TLR7 was increased in patients with moderate or critical COVID-19." (PMID 37310504, 2023). "Although these data are limited, in aggregate they suggest that the various forms of AM all share the characteristic of activating both virus-associated (TLR3, TLR7, TLR8 or TLR9) and bacteria-associated (TLR2 and TLR4) innate receptors with severe COVID-19, KD and MIS-C." (PMID 36769320, 2023). "The X chromosome inactivation escape of TLR7 and the subsequent increased expression of type I IFN may explain in part the observed sex differences concerning severe COVID-19 susceptibility." (PMID 37175768, 2023). "In an extended sample of 3269 patients with critical COVID-19, we identified 57 patients carrying a rare predicted LOF variant at 14 type I IFN-related influenza susceptibility loci (including TYK2) or with biochemically proven TLR7 deficiency." (PMID 37196358, 2023). "Therefore, an X chromosomal gene of interest is TLR7, which has been identified to be involved in type 1 interferon production in COVID-19 needs to be investigated." (PMID 38066751, 2023). "Therefore, TLR7 was expected to be a potential target for COVID-19 cancer therapy based on its abnormal expression in pan-cancer and the significant differences in prognosis and immune environment." (PMID 37362864, 2023). "One study found statistically non-significant differences between patient groups for the TLR7 rs179008 A/T allele in mild, moderate and severe COVID-19." (PMID 37175768, 2023). "We extended the analysis to two other type I IFN-related genes, TLR7 and TYK2, that we had recently found to be associated with critical COVID-19, and to branchpoint (BP) variants with a potentially strong impact on the splicing of the 15 type I IFN-related genes." (PMID 37020259, 2023). "Additionally, TLR7 is also involved in coronavirus disease 2019 (COVID-19), due to the participation of TLR7 in the invasion and infection of the virus." (PMID 36677692, 2023). "Moreover, recent studies have shown that loss-of-function mutations in TLR7 are closely related to severe cases of COVID-195,6, so our structural information of this pathway could be of great significance for the treatment of COVID-19 as well by assisting the identification of activating agents." (PMID 37863913, 2023). "This could be a critical observation because B-cells represent a potential source of pathogenic, TLR7/8 derived, CXCL10 following tissue damage in COVID-19 and could also be a drug target in our PBMC models." (PMID 35261923, 2022). "The IEI affecting the TLR3- and TLR7-signalling pathways established so far could already explain up to 5% of critical COVID-19 cases in men under the age of 60 years." (PMID 35986347, 2022). "We and others identified rare loss-of-function variants in X-chromosomal TLR7 in young men with severe COVID-19 and with no prior history of major chronic diseases, that were associated with impaired TLR7 signaling as well as type I and II IFN responses." (PMID 34952932, 2022).